ACOT12 (acyl-CoA thioesterase 12)
Description:
Catalyzes the hydrolysis of acyl-CoAs into free fatty acids and coenzyme A (CoASH), regulating their respective intracellular levels. Preferentially hydrolyzes acetyl-CoA.
Synonyms: CACH-1; StARD15; CACH; THEAL
Tractability: Small molecule: a structure with a bound ligand is known; it has a high-quality binding pocket.
Gene: Protein-coding gene on chromosome 5 (81,329,862 to 81,394,191, reverse strand). Ensembl gene ENSG00000172497.
Subcellular location: Cytoplasm, cytosol
Subcellular location (Human Protein Atlas): Cytosol; Cytokinetic bridge; Nucleoplasm
Pathways (Reactome):
Metabolism: Mitochondrial Fatty Acid Beta-Oxidation
Gene Ontology:
Molecular function: acetyl-CoA hydrolase activity; identical protein binding; protein binding; ATP binding; lipid binding; medium-chain fatty acyl-CoA hydrolase activity; short-chain fatty acyl-CoA hydrolase activity; thiolester hydrolase activity
Biological process: acetyl-CoA metabolic process; acyl-CoA metabolic process; fatty acid metabolic process
Cellular component: cytosol; cytoplasm
Genetic constraint (gnomAD): Loss-of-function variants: 51 observed, 69.98 expected, observed/expected ratio (o/e) 0.73, 90% interval 0.58 to 0.92. The upper end of that interval is the gene's LOEUF score, 0.92, which puts it in group 3 of 6, group 1 being the genes least tolerant of losing a copy. Missense variants: 730 observed, 699.89 expected, observed/expected ratio (o/e) 1.04, 90% interval 0.98 to 1.11. Synonymous variants: 249 observed, 238.4 expected, observed/expected ratio (o/e) 1.04, 90% interval 0.94 to 1.16.
Homologues: Orthologues: chimpanzee ACOT12 (99% identical), macaque ACOT12 (97% identical), pig ACOT12 (86% identical), dog ACOT12 (86% identical), rabbit ACOT12 (82% identical), mouse Acot12 (81% identical), rat Acot12 (79% identical), guinea pig ACOT12 (76% identical), tropical clawed frog acot12 (59% identical), zebrafish acot12 (52% identical). Paralogues in human: ACOT11 (48% identical), ACOT7 (15% identical).
Diseases named in the same sentence as ACOT12 in open-access papers:
ACOT12 is named in the same sentence as 21 diseases in open-access papers, as found by Europe PMC text mining. Sharing a sentence is not in itself a finding about the gene and the disease. The quoted sentences say what the papers report.
hepatocellular carcinoma (9 papers, 2020 to 2025). A malignant tumor that arises from hepatocytes. "For instance, in a hepatocellular carcinoma model, ACOT12 deficiency-induced acetyl-CoA accumulation specifically increased histone acetylation at the Twist2 locus." (PMID 40589742, 2025). "A previous report suggested that ACOT12 is closely associated with the metastasis of hepatocellular carcinoma (HCC) and survival of HCC patients." (PMID 34285335, 2021). "In hepatocellular carcinoma, ACOT12 regulates cellular acetyl-CoA levels and histone acetylation to promote epithelial-mesenchymal transition and metastasis." (PMID 40978035, 2025). "In a separate study, researchers identified acyl-CoA thioesterase 12 (ACOT12) as a key player in hepatocellular carcinoma (HCC) metastasis." (PMID 38535331, 2024). "On the contrary, ACOT12 is significantly decreased in hepatocellular carcinoma tissues, and was found to epigenetically inhibit epithelial-mesenchymal transition through regulating acetyl-CoA expression, thus suppressing tumor metastasis." (PMID 33362855, 2020). "Interestingly, the latest report demonstrates that ACOT12 plays an inhibitory role in the metastasis of hepatocellular carcinoma and its expression is significantly decreased in highly metastatic HCC tissues." (PMID 35986010, 2022).
glioma (4 papers, 2022 to 2024). A benign or malignant brain and spinal cord tumor that arises from glial cells (astrocytes, oligodendrocytes, ependymal cells). "In addition, a series of gain/loss-of-function experiments revealed that inhibition of ACOT12 could promote the migration and invasion of glioma cells by inducing mesenchymal transition." (PMID 35986010, 2022). "Research has revealed that exosomal miR-155-5p significantly downregulated Acetyl-CoA Thioesterase 12 (ACOT12) and reduced the therapeutic effect of ACOT12 in inhibiting glioma." (PMID 38961907, 2024). "Collectively, our results indicate that GSCs-derived exosomal miR-155-5p is likely to regulate mesenchymal transition and enhance the aggressiveness of glioma by directly targeting ACOT12." (PMID 35986010, 2022). "To explore the role of ACOT12 in glioma, we performed RT-qPCR and IHC experiments to reveal the expression of ACOT12 was significantly decreased in glioma tissues." (PMID 35986010, 2022). "More importantly, we demonstrate that exosomal miR-155-5p derived from GSCs is able to target ACOT12 and accelerate mesenchymal transition, which in turn contributes to the migration and invasion of glioma cells." (PMID 35986010, 2022). "In summary, we demonstrate that GSCs-derived exosomal miR-155-5p plays a critical role in enhancing the aggressiveness of glioma cells by targeting ACOT12 and promoting mesenchymal transition." (PMID 35986010, 2022). "Mechanically, we found that miR-155-5p markedly reduced the expression of acetyl-CoA thioesterase 12 (ACOT12), which played as a tumor suppressor in glioma." (PMID 35986010, 2022). "Downregulation of miR-155-5p attenuated the promoting effect of ACOT12 siRNA on the aggressiveness and mesenchymal transition of glioma cells." (PMID 35986010, 2022). "The results revealed that the expression of ACOT12 was significantly decreased with increasing glioma grade." (PMID 35986010, 2022). "The results of wound healing and Transwell assays indicated that specific inhibition of ACOT12 significantly enhanced the migration and invasion capabilities of glioma cells in vitro." (PMID 35986010, 2022). "Remarkably, we also observed significant inverse correlations between ACOT12 expression and glioma grade by IHC analysis of clinical glioma paraffin sections." (PMID 35986010, 2022). "In conclusion, GSCs-derived exosomal miR-155-5p play a critical role in glioma progression and facilitating tumor aggressive growth by targeting ACOT12 and promoting mesenchymal transition." (PMID 35986010, 2022). "The results showed that the expression of TWIST2 and EMT markers was significantly increased after knockdown of ACOT12 with siRNA, which indicated that depletion of ACOT12 was able to enhance mesenchymal transition in glioma cells." (PMID 35986010, 2022). "Our previous research revealed that glioma stem-like cells derived exosomal miR-155-5p may regulate mesenchymal transition by directly targeting ACOT12 and enhance the invasiveness of glioma." (PMID 38324181, 2024). "Taken together, these findings demonstrate that ACOT12 is the direct target gene of miR-155-5p and may act as a tumor suppressor in glioma." (PMID 35986010, 2022). "Notably, miR-155-5p can repress the expression of ACOT12, which was shown to enhance the invasion and migration ability of glioma cells by facilitating EMT progression." (PMID 35986010, 2022). "We further confirmed the downregulation of ACOT12 in glioma tissues compared to normal controls." (PMID 35986010, 2022). "We then investigated the role of ACOT12 in glioma progression." (PMID 35986010, 2022). "Moreover, depletion of ACOT12 partially rescued the suppressive effect of miR-155-5p inhibition on migration and invasion in glioma cells." (PMID 35986010, 2022). "Thus, we hypothesized that miR-155-5p contributes to migration and invasion in glioma by targeting ACOT12, which in turn promotes mesenchymal transition." (PMID 35986010, 2022).
glioma (continued). "To explore whether the relationship between ACOT12 and EMT is also involved in the progression of glioma, we validated the effect of modulating ACOT12 expression on the expression levels of TWIST2 and other EMT markers, including vimentin and N-cadherin, by RT-qPCR and western blotting." (PMID 35986010, 2022). "Taken together, our findings suggest that ACOT12 can serve as a tumor suppressor by regulating TWIST2 and mesenchymal transition in glioma." (PMID 35986010, 2022). "Thus, we hypothesized that ACOT12 might serve as a tumor suppressor in glioma progression." (PMID 35986010, 2022). "Subsequently, the expression level of ACOT12 was detected by RT-qPCR in four glioma cell lines and HEB cells, and the results indicated that ACOT12 was significantly downregulated in glioma cells." (PMID 35986010, 2022). "Correlation analysis also indicated a negative relationship between expression of ACOT12 and miR-155-5p in glioma tissues." (PMID 35986010, 2022).
diabetes (2 papers, 2023 to 2025). "Considering that in diabetes and after prolonged starvation mobilized lipid is mainly transported in the form of plasma albumin-bound fatty acids, rather than TG, these results suggest that ACOT12 and ACOT8 might be required for rapid degradation of fatty acids in these cases." (PMID 37902629, 2023).
liver cancer (2 papers, 2022 to 2024). An epithelial or non-epithelial malignant neoplasm that arises from the liver. "In a recent liver cancer study, gene manipulation through acyl-CoA thioesterase 12 (ACOT12) led to significant changes in H3 acetylation in different HCC cell lines, making it useful as a prognostic marker." (PMID 39086974, 2022). "The mechanism may be that ACOT12 regulates acetyl-CoA levels and histone acetylation in cancer cells, silencing ACOT12 can induce the expression of oncogene TWIST2 or Snail superfamily Slug, and promote epithelial-mesenchymal transition (EMT) to promote liver cancer metastasis." (PMID 38562172, 2024).
autosomal dominant polycystic kidney disease (1 paper, 2025). Autosomal dominant form of polycystic kidney disease. "In silico analysis using Gene Expression Omnibus (GEO) (GSE7869) confirmed that ACOT12 expression was lower in patients with autosomal dominant polycystic kidney disease (ADPKD) than in normal patients." (PMID 39939783, 2025).
chronic kidney disease (1 paper, 2025). Impairment of the renal function secondary to chronic kidney damage persisting for three or more months. "A significantly decreased level of ACOT12 was observed in kidney samples from human patients with chronic kidney disease as well as in samples from mice with kidney injuries." (PMID 39939783, 2025).
fatty liver (1 paper, 2021). "To determine the time of pathological onset of fatty liver by ACOT12 deficiency, we analyzed adipose and liver tissue in HFD Acot12+/+ and Acot12−/− mice at 2, 4, 6, and 8 weeks." (PMID 34285335, 2021). "However, the pathological onset of fatty liver in Acot12−/− mice suggests the possibility that hepatic fat accumulation may not be influenced by an increase in adipose tissue." (PMID 34285335, 2021). "Here, we found an increased expression level of ACOT12 in fatty liver patients with no alcohol consumption compared to normal patients, suggesting the possible involvement of ACOT12 in NAFLD." (PMID 34285335, 2021).
malignant glioma (1 paper, 2022). A grade III or grade IV glioma arising from the central nervous system. "However, the roles of ACOT12 in malignant glioma progression remain unknown." (PMID 35986010, 2022).
renal fibrosis (1 paper, 2025). A final common manifestation of a wide variety of chronic kidney diseases characterized by glomerulosclerosis and tubulointerstitial fibrosis. "In conclusion, our study demonstrates the functional role and mechanistic details of Acot12 in the progression of renal fibrosis, provides a preclinical rationale for regulating Acot12 expression and presents a novel means of preventing renal fibrosis." (PMID 39939783, 2025).
steatosis (1 paper, 2021). Increased lipid within the cytoplasm of cells. "Among key regulators in acetyl-CoA metabolism, the expression level of ACOT12 was the most significantly altered in both steatosis and NASH compared to normal liver tissue, and its expression gradually changed during the progression of NAFLD." (PMID 34285335, 2021).
Ureteral obstruction (1 paper, 2025). Obstruction of the flow of urine through the ureter. "Acot12 deficiency induces lipid accumulation and fibrosis in mice subjected to unilateral ureteral obstruction (UUO)." (PMID 39939783, 2025).
tumor (6 papers, 2020 to 2025). "Acyl-CoA thioesterase 12 (ACOT12), a crucial molecule involved in cellular energy metabolism, glucose metabolism, as well as tumor development and progression." (PMID 40303979, 2025). "A total of 75 mRNAs were predicted to be targeted by miR-155-5p, potentially including acetyl-CoA thioesterase 12 (ACOT12), which was first reported as a tumor suppressor by regulating EMT in HCC." (PMID 35986010, 2022). "ACOT12 appears to be the major enzyme responsible for hydrolysis of acetyl-CoA35, which induces tumor cell metastasis." (PMID 35399720, 2022). "We found that the expression level of ACOT12 was lower in ICC tissues than para-tumor tissues." (PMID 35399720, 2022). "To investigate the role of acetyl-CoA metabolic alteration in ICC, we firstly evaluated the expression level of acetyl-CoA hydrolysis gene ACOT12 across cancers with tumor and normal samples from the TCGA public database, and found that ACOT12 down-regulated most significantly in ICC." (PMID 35399720, 2022). "Next, we systematically explored the relationship between the expression of 37 common DEGs in tumor tissues and OS rate in TCGA and constructed a novel prognosis-related model composed of five genes (AURKA, PZP, RACGAP1, ACOT12 and LCAT)." (PMID 34336648, 2021). "The downregulation of acyl CoA thioesterase 12 (ACOT12) contributes to the accumulation of acetyl-CoA, which leads to increased histone acetylation and activation of the TWIST2 gene, thereby promoting epithelial–mesenchymal transition and tumor metastasis." (PMID 41551149, 2025). "Next, we systematically explored the relationship between the expression of 37 common DEGs in tumor tissues and overall survival (OS) rate of HCC patients in TCGA and constructed a novel prognostic model composed of five genes (AURKA, PZP, RACGAP1, ACOT12 and LCAT)." (PMID 34336648, 2021).
cancer (4 papers, 2017 to 2024). A tumor composed of atypical neoplastic, often pleomorphic cells that invade other tissues. "During cancer, increased levels of acyl-CoA thioesterase 12 (ACOT12), an enzyme which generates acetate from acetyl-CoA, can be found in the liver." (PMID 38731909, 2024).
kidney disease (1 paper, 2025). "Acot12 KO (Acot12−/−) mice previously generated via RGEN-induced mutation of the Acot12 gene were used to understand the role of ACOT12 in kidney disease pathogenesis." (PMID 39939783, 2025). "This early lipid deposition suggests that dysregulated lipid metabolism due to ACOT12 deficiency may contribute to the initiation and progression of kidney fibrosis, highlighting the role of lipid accumulation as an early pathogenic event in kidney disease." (PMID 39939783, 2025). "In summary, we used transgenic mouse models to delineate the biological functions of ACOT12 in the pathogenesis of kidney diseases, particularly kidney fibrosis." (PMID 39939783, 2025). "However, the pathophysiological role and mechanism of action of ACOT12 in kidney diseases remain unknown." (PMID 39939783, 2025).
ACOT12 also shares sentences with these, for which no sentence is quoted: breast carcinoma (1 paper); Impaired glucose tolerance (1); Insulin resistance (1); intrahepatic cholangiocarcinoma (1); nonalcoholic fatty liver disease (1); polycystic kidney (1); tumors of the nervous system (1).